CD4 (CD4 molecule)
Diseases named in the same sentence as CD4 in open-access papers (continued):
Sharing a sentence is not in itself a finding about the gene and the disease.
viral infection (continued). "The most important are, among others, the deregulation of immune response to viral infection through the cytokine storm (hypercytokinemia) and the reduced production of IFN-γ as a consequence of a decrease in CD4+ lymphocyte to Th1 subtype differentiation." (PMID 37762882, 2023). "The study focused on identifying CD4+ epitopes in the DENV-1 proteome that can activate CD4+ T cells, which play a critical role in the adaptive immune response against viral infections." (PMID 37987878, 2023). "CD4+ cells also induce the development and maintenance of protective effector memory CD8+ cell responses during viral infection or immunization." (PMID 38067030, 2023). "To investigate if the viral infection regulated the transcription of caspases, we performed whole cell transcriptome analyses by RNA-Seq of HIV-1BAL infected primary CD4 T cells." (PMID 36780482, 2023). "Fractional doses of the 17D-213 yellow fever vaccine were sufficiently immunogenic and safe demonstrating non-inferiority to the standard vaccine dose in HIV-infected individuals with CD4+ T cell counts of at least 200 cells per mL." (PMID 37127045, 2023). "During virus infection, MHC I and II molecules are responsible for presenting antigen peptides produced by virus particles to CD8+ and CD4+ T cells to activate cellular immune response of the host." (PMID 36960283, 2023). "The upregulation of IFN-related genes in B, CD14+, CD4+, and CD8+ cells is indicating that the host is detecting the presence of the viral infection and consequently activating the IFN response." (PMID 37920474, 2023). "IFNγ-producing T cells, i.e., CD4+ Th1 and CD8+ cytotoxic T lymphocytes, are crucial in viral infections." (PMID 37371616, 2023). "In following sections, we describe how metformin regulates the interface of metabolism and immune function in the CD4 and CD8 T cells under the various diseases condition, such as virus infection, autoimmune diseases, aging and cancers." (PMID 36614197, 2023). "If there is persistent viral infection or stimulation from tumor antigens, LAG-3 is expressed simultaneously with other immune checkpoints on the surfaces of both CD4+ and CD8+ T cells, indicating possible T cell dysfunction." (PMID 37841254, 2023). "Previous studies have shown that CD4 T cells expressing CD161 are depleted from blood during HIV and SIV infections because of viral infection and redistribution to mucosal tissues along with significant loss of IL-17 functions." (PMID 37766350, 2023). "Since then, studies reporting on CD4+ CTL in both humans and animal species steadily increased in the context of viral infections and, recently, also in cancer." (PMID 37965314, 2023). "Increased CD4+ and CD8+ T cells in the primary immune response to bluetongue virus infection in sheep trigger a T-cell response to resist viral infection." (PMID 38187382, 2023). "Extensive research over the last years has advanced our understanding of hepatic conventional CD4+ and CD8+ T cells and unconventional T cell subsets and their functions in the liver environment during acute and chronic viral infections." (PMID 36992265, 2023). "Our results concur with previous studies demonstrating depletion of CD161-expressing CD4 T cells from blood during HIV and SIV infections, primarily due to viral infection and redistribution to mucosal tissues." (PMID 37766350, 2023). "Distinct T cell populations, including CD4+CD8− (T helper cells, CD4+) and CD4−CD8+ (cytotoxic T cells, CD8+ cells), often play important roles in the host’s defense against viral infections through the development of the adaptive immune response." (PMID 36851421, 2023). "Strong inhibitory KIR3DL1 ligation has been demonstrated to improve NK cell activation and antibody-dependent cellular cytotoxicity (ADCC), inhibit HIV-1 replication in autologous infected CD4+ T cells, and enhance survival of CD8+ T cells in viral infection." (PMID 35235807, 2022).
viral infection (continued). "We have previously shown that there are relatively high expression of cytotoxic lymphocyte markers in HIV-specific and CMV-specific CD4 T cells, as well as CD4 CTL found in other viral infections (reviewed recently in)." (PMID 36544780, 2022). "The well-known role of TNF-α in the control of viral infection and the strong IFN-γ−/TNF-α+ response observed for SRAS-CoV-2-specific CD4+ T-cells described here would be in favor of such a possibility." (PMID 35335079, 2022). "Although exhausted CD4+ and CD8+ T cells share some common features in chronic viral infection, their exhaustion profiles are distinct." (PMID 35432304, 2022). "Research determined that the upregulated ratio of CD4+/CD8+ occurred the pivotal contributing factor in autoimmune diseases, virus infections and cancers." (PMID 36457713, 2022). "While various innate and adaptive immune cell types have been identified as IL-10 producers, CD4+ and CD8+ T cells are important sources of IL-10 during viral infections." (PMID 35634328, 2022). "The observation that expanded clones of latent cells are frequently found in the CD4+ TEM compartment is consistent with the finding that clones of latent cells and TEM cells develop in response to chronic viral infection." (PMID 36070690, 2022). "Cellular immune response, and in particular that involving the IFN-γ- producing CD4 and CD8 T lymphocytes, is crucial for fighting against viral infections including SARS-CoV-2 infections." (PMID 35893838, 2022). "Although CD4+ and CD8+ T cells respond to viral infection, CD4+ T cells are unable to differentiate or expand as rapidly as CD8+ T cells." (PMID 36560733, 2022). "There is increasing evidence that IL-27 is a potent inducer of IL-10 production from CD4+ and CD8+ T cells in a variety of viral infections, thereby having implications on antiviral immune responses and viral clearance." (PMID 35634328, 2022). "Peripheral blood mononuclear cells obtained from patients with other viral infections, such as HBV, and depleted of CD4+ CD25 + reg T lymphocytes release growing levels of IFN-γ after stimulation with viral antigens." (PMID 36694588, 2022). "Significant reductions in IL-10-producing CD4+ and CD8+ T cells are observed during viral infection in il27ra-/- and ebi3-/- mice compared to their WT counterparts." (PMID 35634328, 2022). "We showed that while PSGL-1 restrained virus-specific CD4+ and CD8+ T cells during chronic viral infection, it was also necessary for their maintenance in the persistently infected host." (PMID 35774790, 2022). "To investigate the cell-intrinsic role of PSGL-1 in T cells over the course of chronic viral infection, we co-injected small numbers (1-2 x103) of TCR transgenic (Tg) CD4+ and CD8+ T cells specific for LCMV into WT mice." (PMID 35774790, 2022). "In T-cells, IFN-α/β promotes survival of activated CD4+ and CD8+ T cells in vitro, CD8+ T cells differentiation and expansion, and clonal expansion of CD4+ and CD8+ T cells in response to viral infection in vivo." (PMID 36726783, 2022). "Mechanistically, for HT, a high affinity with the CD4 cellular receptor has been shown, e.g., preventing human immunodeficiency virus (HIV) from bonding during viral infection." (PMID 36012942, 2022). "The expression of CD38 and HLA-DR markers on the surface of CD4+ and CD8+ T cells reflects the activation of both cell subsets in response to viral infections." (PMID 35898494, 2022). "Tcf1 plays an essential role in controlling T cell development, the differentiation of specific CD4 T helper (Th) subsets, and the formation of memory and stem-cell-like CD8 T cells following various types of viral infections." (PMID 35983065, 2022). "Expression of those TLRs in CD4 + and CD8 + T cells is related to cell activation, viral infection and IFN stimulation." (PMID 36224474, 2022).
viral infection (continued). "The adaptive immune system is activated by specific antigens and is mainly composed of CD4+ T cells, CD8+ T cells and B cells, which play different roles in viral infection." (PMID 36389144, 2022). "Following the clearance of virus in acute viral infection, virus-specific memory CD8+ T cells can persist for a very long period at a stable level, whereas virus-specific memory CD4+ T cells gradually decay over time." (PMID 35909969, 2022). "cDC1s have been suggested as targets of CD4 T cells in an in vitro analysis of CD4 T helper cell-dependent CD8 T cell responses and by intravital imaging during viral infection." (PMID 34480145, 2022). "It has been reported that IL-23 plays a role in the long-term establishment of memory CD4+ T cells in the early phase of the immune response and induces strengthened sustained CD8+ CTL during viral infection." (PMID 35468944, 2022). "Since both T helper CD4+cells and T cytotoxic CD8+cells are involved during viral infections, including coronavirus, their levels were determined in each patient’s sample." (PMID 35196808, 2022). "CD4:CD8 ratio in normal individuals is 2:1 and it gets inverted to 1:1 in some viral infections due to the increase in CD8+ T cells as shown by research into the immune response." (PMID 35898494, 2022). "A number of significant changes were also noted following challenge in CD4+CD8+ double positive T cells, a population noted as playing a role in fighting viral infections such as ASFV in swine." (PMID 36558773, 2022). "Thus, restoring mtDNA topology during chronic viral infection may rescue CD4 T cell functions." (PMID 36405960, 2022). "Moreover, in line with increased TCR signaling during chronic viral infection, we observed a conserved increase in the expression of AP-1 family members Jund and Junb, as well as in Cd69, Nr4a2, and Tox gene expression across all CD4+ T cell subsets during LCMV Cl13 infection." (PMID 36255051, 2022). "Particularly, both CD4+ and CD8+ T cells have been reported to control multiple viral infections and provide protection against subsequent re-infections by generating immunological memory." (PMID 35746545, 2022). "The presence of cytotoxic CD4+ T cells specific for SARS-CoV-2 in murine models has been reported, and it correlates with protection in some viral infections, such as West Nile fever." (PMID 36439169, 2022). "However, the literature shows that certain viral infections, such as measles, can exacerbate pulmonary TB, probably because of depressed cellular immunity since TB normally requires cellular immunity, particularly CD4-mediated immunity, in addition to the patient being transiently immunosuppressive." (PMID 36136658, 2022). "Significantly increased splenic CD4+ and CD8+ responses to viral and tumor antigens reduced by day 21, likely as viral infection resolved and tumor burden decreased." (PMID 35795092, 2022). "As suggested by the differentiation state of these cells and previous reports of CD101 expression on CD8 in viral infection, we demonstrate that CD101+ CD4 T cells are highly enriched for expression of immunosuppressive receptors in lymphoid tissue during ART." (PMID 35867722, 2022). "Type I interferons α and β are essential cytokines in the early stages of viral infection for the activation and differentiation of CD8+ T-cells, but a long duration release can induce CD4+ T-cell exhaustion." (PMID 36471834, 2022). "However, vaccine-induced CD4+ T cell-mediated immunopathology could be ameliorated by co-transfer of an LCMV-specific neutralizing monoclonal antibody to vaccinated mice prior to viral infection." (PMID 35788221, 2022). "This indicates the important role of CD4+ T cells in controlling SARS-Cov infection, as well as other viral infections." (PMID 35196808, 2022). "When HA29- and HI12-scDbs were incubated with CTLs and newly infected CD4+ T cells, HA29-scDb suppressed viral infection in a 72-h coculture." (PMID 35394875, 2022).
viral infection (continued). "SARS-CoV-2-specific CD4+ Th1 cells that produce IFNγ, TNF-ɑ, and/or IL-2 can be detected in vaccinators or convalescents, which is similar to other viral infections." (PMID 36032096, 2022). "T-cell-inducing vaccines have been developed to induce CD4+ and/or CD8+ cells to give a protective adaptive immune response against viral infection." (PMID 34579246, 2021). "We did identify 294 DML sites in CD4+ T lymphocytes that were associated with AHI at host genes such as EZR, MDM2, and PIK3C2A that play a role in viral activity suggesting that HIV-1 may be modifying CD4+ T lymphocytes DNA methylation states to promote viral infection and replication." (PMID 34388205, 2021). "In this study, the upregulated expression of CTLA-4, LAG-3, 2B4, and TIGIT were observed in CD8+ T cells and CD4+ T cells of mice infected with FMDV, which would inhibit T-cell proliferation and promote T-cell apoptosis during virus infections." (PMID 34960627, 2021). "CD4 T cells are well known for their supportive role in CD8 T cell and B cell responses during viral infection." (PMID 34959486, 2021). "Nonetheless, a local interaction between CD8 and CD4 T cells is required for optimal TRM cell responses following both acute and persistent viral infections." (PMID 33854506, 2021). "Animal models have shown that CD4+ and CD8+ T cells residing in the respiratory tract are important for local protection immediately after viral infection." (PMID 34452006, 2021). "Antigen-specific CD4+ T cells not only prime B cells and launch humoral immune responses against SARS-CoV-2 but also provide helper function to CD8 T cells in viral infections and cancer." (PMID 34725257, 2021). "In humans, less is known about the presence and functionality of Tfh cells during viral infections, especially during HCV infection, as the peripheral HCV-specific CD4 T cell population rapidly collapses with progression to chronicity." (PMID 34659236, 2021). "CD4+ and CD8+ antigen-specific T cell populations expand during the first days to weeks following acute viral infection." (PMID 33430234, 2021). "Recent studies suggest that T lymphocytes, particularly CD4+ T and CD8+ T cells, are affected by SARS-CoV-2, CD4+ and CD8+ T cells play a fundamental role in controlling viral infections and maintaining cellular, humoral and cytotoxic immune responses." (PMID 33937149, 2021). "Here, we reported that Damage-specific DNA binding protein 1 (Ddb1) was required for expansion of CD4+ helper T cells including TFH and Th1 cells, germinal center response, and antibody response to acute viral infection." (PMID 34526995, 2021). "Nanoparticle-based vaccine formulations have shown their efficacy in the generation of CD4+ and CD8+ T cell responses, the latter is critical to control intracellular infections, particularly viral infections." (PMID 34579186, 2021). "In our results, the ratio of CD4 to CD8 was generally less than 1, as it happens in other viral infections." (PMID 34573988, 2021). "In an in vitro infection model, re-emergence of viral infection after removal of cART was inhibited significantly by CAR+ T-cells and LRA-treated CD4+ T-cells isolated from infected patients were lysed efficiently by CAR+ T-cell mediated cytotoxicity." (PMID 34452428, 2021). "While CD8 T-cell function can become compromised during chronic viral infection, HTLV-1 predominantly infects CD4 T cells, so it was important to consider NCR expression in both T-cell populations and in various differentiated T-cell subsets." (PMID 33767694, 2021). "On day 3 post viral infection, SMARTA CD4+ T cells of both genotypes showed similar upregulation of T-cell activation markers CD69 and CD44, and downregulation of CD62L." (PMID 33637761, 2021). "The role of adaptive cell-mediated immunity, CD4+ and CD8+ T cells, in a viral infection, is well understood." (PMID 33923155, 2021).
viral infection (continued). "During viral infections, DC-SIGN was shown to bind gp120 on HIV using DC as a shuttle for the trans-infection of CD4+ T cells." (PMID 34638920, 2021). "In many chronic viral infections, including TMEV, FoxP3+CD4+ T cells appear to contribute to the pathogenesis by inhibiting protective T cell function and consequently promoting viral persistence." (PMID 34067536, 2021). "Here, we showed that deletion of Ddb1 in effector CD4+ T cells led to impaired TFH and Th1 cell generation due to defect of T-cell expansion upon acute viral infection." (PMID 34526995, 2021). "However, the changes in the frequency of CD4+CD25+ Tregs in the spleen and bursa of Fabricius were not exactly similar to that in the blood and thymus, which suggested that the CD4+CD25+ Tregs in these organs might be redistributed during anti-viral infection by the immune system." (PMID 34526112, 2021). "Furthermore, antigen-experienced CD4+ cytotoxic lymphocytes (CTLs) may play an important role in controlling chronic viral infections, such as Epstein-Barr virus (EBV), cytomegalovirus (CMV), and human immunodeficiency virus (HIV), as well as certain malignancies." (PMID 34445118, 2021). "As CD4+ and CD8+ T cells are important for protection against viral infections, including FMDV, we assessed the activation of cell-mediated immune response in KST0669-vaccinated mice." (PMID 33466461, 2021). "Published studies have shown that CD4+ T effector cells in exposed or vaccinated individuals can express perforin/FasL and exert CTL-like activities against viral infections." (PMID 33732233, 2021). "In viral infections, protective antiviral immunity is related to IFN-γ secretion, virus-specific CD4+ and CD8+ T cell responses." (PMID 34960654, 2021). "The expression of CD4 and CCR5 on microglia facilitates virus infection in an analogous manner to that observed in leukocytes." (PMID 34452054, 2021). "Bacterial diseases, primarily pneumonia and tuberculosis, affected the majority of HIV-infected individuals in all CD4 cell count strata, contrasting with HIV-negative individuals who mostly presented with viral diseases." (PMID 32896654, 2021). "MHC-I and MHC-II molecules play a critical role in the control and clearance of viral infections by presenting peptides to CD8+ and CD4+ T cells, respectively, and further leading to the initiation of an adaptive immune response." (PMID 35126380, 2021). "Both CD4+ and CD8+ T cells participate in the host adaptive immune response against bacterial and viral infections." (PMID 34603402, 2021). "RIG-I-like receptors (RLRs): RIG-1, LGP2, and MDA-5 that sense viral infection were found to be predominant in CD4+, CD8+, and CD14+ cell subsets at 5 dpv in goats and in CD4+ and CD14+ cell subsets of sheep." (PMID 33785572, 2021). "TSLP has been studied extensively in the context of TH2-type immunity, and we previously demonstrated that TSLP can act directly on CD4+ and CD8+ T cells, but its roles in CD8+ T cell responses during viral infection remain poorly understood." (PMID 33439121, 2021). "Nevertheless, our findings identify, for the first time, the role of the GAS5-miR-21 axis in CD4 T cell dysregulation in PLHIV and shed light on the molecular aspects of immunomodulation during human viral infections." (PMID 33776993, 2021). "Preclinical data show that prenatal/early postnatal exposure to AhR ligands leads to a reprogramming of the CD4+ and CD8+ T cell responses to viral infection, via the long-term maintenance of alterations in DNA methylation." (PMID 33562472, 2021). "During viral infections, neutrophils express HLA-DR (MHC class II), CD80, and CD40, which contribute to antigen-specific CD4+ T-cell response." (PMID 34411088, 2021). "We found that O-linked α1,2 mannosylation of Bl-Eng2 is chiefly recognized by Dectin-2 and augments the expansion, differentiation, tissue residency of Ag-specific CD4+ and CD8+ T cells in the lung and protects mice against fungal and viral infection." (PMID 33735218, 2021).